GPR55 (G protein-coupled receptor 55)
Diseases named in the same sentence as GPR55 in open-access papers (continued):
Sharing a sentence is not in itself a finding about the gene and the disease.
melanoma (4 papers, 2014 to 2021). A malignant, usually aggressive tumor composed of atypical, neoplastic melanocytes. "AEA is the CB1/CB2 receptor agonist, TRPV1 agonist, putative GPR55 agonist, induced in the A375 melanoma cell line a concentration-dependent cytotoxicity and decrease in cells viability." (PMID 34264513, 2021). "First, we identified the presence of CB1, CB2(A), GPR18 (transcriptional variant 1) and GPR55 receptors in brain endothelial cells, while melanoma cells expressed CB1, CB2(A), GPR18 (transcriptional variants 1 and 2), GPR55 and GPR119." (PMID 24815068, 2014). "In another study, 1–10 μM AM251 (48–72 h) induced apoptosis and G2/M cell cycle arrest in A375 human melanoma cells in a GPR55-, TRPA1-, and COX2-independent manner, whereas the combination of AM251 with COX2-inhibitor celecoxib produced a synergistic antitumor activity." (PMID 30845666, 2019). "Expression of CB1, CB2, GPR18, GPR55 and GPR119 were identified in A2058 human amelanotic melanoma cell line." (PMID 30845666, 2019). "Indeed, miR-4286 inhibition resulted in degradation of folylpolyglutamate synthase, RNA polymerase I-specific transcription initiation factor, apelin, G-protein-coupled receptor 55, and high-mobility group A1 protein mRNA in BRO melanoma cells, as measured by real-time PCR." (PMID 28005927, 2016). "Since besides CB1 and GPR55, AM251 can also target GPR18, one might speculate that modulating activity of this receptor may be responsible for the beneficial effects, especially, since GPR18 (as well as GPR119) was found to be overexpressed at the mRNA level in melanomas as compared to nevi." (PMID 30845666, 2019).
squamous cell carcinoma (4 papers, 2016 to 2025). A carcinoma arising from squamous epithelial cells. "GPR55 is detectable in keratinocyte lineages and is up-regulated in squamous-cell carcinoma, where it engages extracellular signal–regulated kinase (ERK), AKT, and Ras homolog family member A (RhoA) pathways to drive proliferation." (PMID 41304852, 2025). "GPR55 is upregulated in melanoma and squamous cell carcinoma, implicating it in the pathology of pigment cells." (PMID 41304852, 2025). "However, the involvement of endocannabinoids in carcinogenesis and the druggability of GPR55 as a target for the treatment of squamous cell carcinoma were not investigated in this study, as this would require a pharmacological experimental approach with GPR55-inhibiting cannabinoids." (PMID 35406541, 2022).
atopic dermatitis (3 papers, 2021 to 2023). "Semiquantitative evaluation of the density of CB2R, GPR55, TRPV1, and TRPA1 immunoreactivity in different cellular elements of the skin of dogs with atopic dermatitis (AD-dogs)." (PMID 36187821, 2022). "A similar change in GPR55 expression was demonstrated in epidermal shaves of non-lesional skin of patients suffering from moderate to severe early-onset persistent atopic dermatitis versus healthy volunteers." (PMID 34948125, 2021).
mood disorder (3 papers, 2017 to 2022). A cognitive disorder a disturbance in which the person's mood is hypothesized to be the main underlying feature. "Thus, activation of GPR55 links the RhoA-ROCK and PLC-PKC pathways to the development of mood disorders, evident by alteration of the expression of glutamate receptors." (PMID 28800762, 2017).
myocardial infarction (3 papers, 2019 to 2025). Gross necrosis of the myocardium, as a result of interruption of the blood supply to the area, as in coronary thrombosis. "In the context of myocardial infarction, GPR55 knockout mice developed worse LV dilation and a more extensive infarct area." (PMID 40562493, 2025). "Following acute myocardial infarction, GPR55 deficiency did not affect the initial infarct size in our study." (PMID 34257332, 2021). "While classical cannabinoid receptors are known to crucially impact on myocardial infarction (MI) repair, a function of the cannabinoid-sensitive receptor GPR55 herein is poorly understood." (PMID 34257332, 2021).
myocardial ischemia (3 papers, 2019 to 2025). A disorder of cardiac function caused by insufficient blood flow to the muscle tissue of the heart. "The Rho/ROCK pathway, which acts upstream of GPR55, exacerbates injury in myocardial ischemia-reperfusion, while ROCK ischemia suppresses injury in hepatic ischemia-reperfusion." (PMID 37176603, 2023).
neuroblastoma (3 papers, 2022 to 2026). Neuroblastoma (NB) is the most common solid, extracranial childhood tumor. "Previous studies found promising GPR55-dependent anti-inflammatory and anti-oxidative properties of KIT C in human SK-N-SH neuroblastoma cells and primary mouse microglia." (PMID 38931342, 2024).
non-small cell lung carcinoma (3 papers, 2015 to 2022). A group of at least three distinct histological types of lung cancer, including non-small cell squamous cell carcinoma, adenocarcinoma, and large cell carcinoma. "Overexpression of miR-675-5p inhibits tumor growth, attenuates proliferation, migration, and invasion, and induces G1 cell cycle arrest of non-small-cell lung cancer cells both in vitro and in vivo via direct targeting of GPR55, through inhibition of ERK pathway." (PMID 36291926, 2022).
psoriasis (3 papers, 2018 to 2022). An autoimmune condition characterized by red, well-delineated plaques with silvery scales that are usually on the extensor surfaces and scalp. "In our patients, the expression of the receptor GPR55 was elevated in both forms of psoriasis while the expression of the receptor CB2 was elevated only in Ps in contrast to the CB1 receptor, which was increased only in PsA patients." (PMID 30301214, 2018). "A recent study reported that higher levels of GPR55 are found in granulocytes from psoriasis and psoriatic arthritis patients than in the control group, suggesting that cannabinoids with GPR55-antagonising effects, as is the case with CBD, may be beneficial for these indications." (PMID 36552866, 2022). "Natural killer (NK) cells and monocytes activated by GPR55 can produce proinflammatory factors such as IL-12 and TNF-α, which have critical roles in the pathogeneses of psoriasis and CVDs." (PMID 33602246, 2021).
schizophrenia (3 papers, 2017 to 2024). A major psychotic disorder characterized by abnormalities in the perception or expression of reality. "Schizophrenia is associated with inflammatory processes and altered microglial activation; therefore, activation of GPR55 and modulation of inflammatory processes via this receptor might be beneficial in treating schizophrenia." (PMID 38796643, 2024). "For schizophrenia, some authors suggest potential antipsychotic effects of CBD via inhibition of GPR55." (PMID 38796643, 2024). "However, there is a lack of research regarding the possible involvement of GPR55 in the development and progress of schizophrenia." (PMID 38796643, 2024).
anorexia nervosa (2 papers, 2011 to 2024). A disorder most often seen in adolescent females characterized by a refusal to maintain a minimally normal body weight, an intense fear of gaining weight, a disturbance in body image, and, in postmenarcheal females, the development of amenorrhea. "Similarly, an association between the GPR55 polymorphism Gly195Val and anorexia nervosa in a study comprising 235 patients and 1244 controls in a female Japanese population." (PMID 32143540, 2011). "Finally, a couple of recent articles have studied association of CNR2 and GPR55 polymorphisms with anorexia nervosa." (PMID 32143540, 2011). "Functional polymorphisms of GPR55 led to altered Erk1/2 phosphorylation in Chinese hamster ovary (CHO) cells, and GPR55 Val195 polymorphism was associated with increased vulnerability to anorexia nervosa in Japanese females." (PMID 38796643, 2024).
autism (2 papers, 2021 to 2025). Persistent deficits in social interaction and communication and interaction as well as a markedly restricted repertoire of activity and interest as well as repetitive patterns of behavior. "Notably, LPI can activate the CNS regulatory factor GPR55, which subsequently activates ERK1/2, potentially contributing to the pathophysiology of autism." (PMID 40998031, 2025). "Thus, it is hypothesized that VPA induction may enhance the synthesis of LPI, increase the expression of gpr55, and subsequently activate the ERK1/2 signaling pathway, potentially contributing to the development of autism." (PMID 40998031, 2025).
heart failure (2 papers, 2014 to 2025). Inability of the heart to pump blood at an adequate rate to meet tissue metabolic requirements. "Furthermore, GPR55 was shown to play a role in the influx of calcium in the endothelial cells; it plays a role in mechanical hyperalgesia associated with inflammation and neuropathic pain, and with cardiovascular function and heart failure." (PMID 41394912, 2025). "Taken together, this may suggest a role for GPR55 in the control of adrenergic signalling in the heart and potentially a role for this receptor in the pathogenesis of heart failure." (PMID 25275556, 2014). "This intrinsic inability of the heart to maintain systolic function appears to be due to maladaptive adrenergic signalling, which may suggest some interplay/crosstalk between GPR55 and adrenoceptors and a possible role for GPR55 in the pathogenesis and/or progression of heart failure." (PMID 25275556, 2014).
joint disease (2 papers, 2023). "The discovery of cannabinoid receptors (CB1R, CB2R, GPR55) in the synovial tissue of middle-aged dogs provides compelling molecular evidence supporting the use of cannabinoids for treating and delaying joint diseases." (PMID 37760233, 2023). "While the exact role of GPR55 in joint health is still being elucidated, current evidence suggests that it is a promising target for the development of novel therapeutics for joint disorders." (PMID 37760233, 2023).
lung carcinoma (2 papers, 2015 to 2016). "Therefore, down-regulation of miR-675-5p suppresses lung cancer progression and metastasis through regulation of GPR55." (PMID 25889562, 2015). "Therefore, miR-675-5p could be a novel tumor-suppressor miRNA, and its down-regulation might contribute to lung cancer progression and metastasis through regulating GPR55 function." (PMID 25889562, 2015).
lymphoma (2 papers, 2017 to 2021). A malignant (clonal) proliferation of B- lymphocytes or T- lymphocytes which involves the lymph nodes, bone marrow and/or extranodal sites. "The GPR55 gene is abundantly expressed in lymphoid organs, such as spleen and thymus, and hyper-expressed in many human cancer cells, including B-cell multiple myeloma, lymphoma, and lymphoblastoid cells." (PMID 28029647, 2017).
metastatic disease (2 papers, 2016 to 2021). "The demonstration that GPR55 expression is increased in both types of EC, especially in the more aggressive Type 2 form, may also provide additional prognostic markers and therapeutic targets for individualised treatment and give hope for those women with metastatic disease." (PMID 34324032, 2021).
non-alcoholic steatohepatitis (2 papers, 2020 to 2025). "As an example, recent studies identified a crucial role for LPI signaling in metabolic disorders leading to nonalcoholic steatohepatitis, a degenerative disorder of the liver that leads to steatosis and fibrosis in which both GPR55 and LPI are upregulated." (PMID 33167441, 2020).
osteoarthritis (2 papers, 2023 to 2025). A noninflammatory degenerative joint disease occurring chiefly in older persons, characterized by degeneration of the articular cartilage, hypertrophy of bone at the margins and changes in the synovial membrane. "This suggests that GPR55 might be involved in the regulation of synovial inflammation and joint damage associated with rheumatoid arthritis and osteoarthritis." (PMID 40429822, 2025).
osteoporosis (2 papers, 2021). A condition of reduced bone mass, with decreased cortical thickness and a decrease in the number and size of the trabeculae of cancellous bone (but normal chemical composition), resulting in increased fracture incidence. "Our data indicate that GPR55 represents a target for development of novel therapeutic approaches for treatment of pathological conditions caused by osteoclast-exacerbated bone degradation, such as in osteoporosis or during establishment of bone metastases." (PMID 33902596, 2021).
overactive bladder (2 papers, 2020 to 2021). Symptom of overactive detrusor muscle of the urinary bladder that contracts with abnormally high frequency and urgency. "Recently, evidence has suggested that GPR55, a possible third CBR, may also be a potential target for treatment of overactive bladder since the GPR55 agonist O-1602 significantly reduces DO in rats." (PMID 34290614, 2021).
pancreatic ductal adenocarcinoma (2 papers, 2021 to 2024). An infiltrating adenocarcinoma that arises from the epithelial cells of the pancreas. "We intended to uncover the role of GPR55 in tumor immunity in a model of pancreatic ductal adenocarcinoma (PDAC)." (PMID 39885986, 2024).
psoriatic arthritis (2 papers, 2018 to 2022). Joint inflammation associated with psoriasis. "Increased endocannabinoids and G protein-coupled receptor 55 were observed in both forms of the disease while expression of the cannabinoid type 1 receptor (CB1) was increased only in patients with psoriatic arthritis, which is opposite to the cannabinoid type 2 receptor." (PMID 30301214, 2018).
Rett syndrome (2 papers, 2021 to 2023). A severe neurodevelopmental disorder affecting the central nervous system. "A structurally related cannabinoid to CBD, cannabidivarin, acted as an antagonist at GPR55, and it enhanced social behavior in the Rett’s syndrome mice." (PMID 37273836, 2023). "GPR55 is involved in spatial learning and memory, and its expression is doubled in Rett’s syndrome mice exhibiting deficits in social behavior." (PMID 37273836, 2023). "GPR55 was found to be increased in the Rett syndrome mouse hippocampus, suggesting that GPR55 antagonists could be potential pharmacological agents for this pathology." (PMID 34834237, 2021).
rheumatoid arthritis (2 papers, 2021 to 2025). A chronic, systemic autoimmune disorder characterized by inflammation in the synovial membranes and articular surfaces. "Therefore, this study utilized CID16020046 to investigate the role of GPR55 in a murine collagen-induced rheumatoid arthritis model." (PMID 40429822, 2025). "In conclusion, inhibiting GPR55 alleviates the symptoms of collagen-induced rheumatoid arthritis, indicating that GPR55 may serve as a promising therapeutic target for autoimmune diseases by preventing its activation." (PMID 40429822, 2025). "In conclusion, blocking GPR55 alleviates collagen-induced rheumatoid arthritis symptoms by suppressing Th1 and Th17 cells in the spleen and pro-inflammatory cytokines in the joints, suggesting that GPR55 is a potential therapeutic target for autoimmune inflammatory diseases." (PMID 40429822, 2025). "Given the elevated levels of endogenous ligands, LPIs, in the blood of rheumatoid arthritis patients, it is plausible that the activation of GPR55 by LPIs contributes to inflammatory and autoimmune processes, as demonstrated through the use of the GPR55 antagonist CID16020046 in this study." (PMID 40429822, 2025). "This study aimed to investigate the role of GPR55, using its antagonist, CID16020046, in a collagen-induced rheumatoid arthritis mouse model." (PMID 40429822, 2025). "Although human SW982 synovial cells were studied, extensive studies on GPR55 in chondrocytes, osteoclasts, macrophages, and neutrophils are necessary to elucidate the mode of action of CID16020046 in rheumatoid arthritis." (PMID 40429822, 2025). "In our current research, we present novel evidence that the GPR55 antagonist CID16020046 can inhibit lipopolysaccharide-induced expression of pro-inflammatory cytokines in SW982 human synoviocytes and mitigate collagen-induced rheumatoid arthritis in DBA-1J mice." (PMID 40429822, 2025).
steatosis (2 papers, 2020 to 2021). Increased lipid within the cytoplasm of cells. "The present study reports GPR55–dependent fat accumulation in hepatocytes and steatosis in the liver." (PMID 33803038, 2021).
triple-negative breast carcinoma (2 papers, 2016 to 2021). An invasive breast carcinoma which is negative for expression of estrogen receptor (ER), progesterone receptor (PR), and human epidermal growth factor receptor 2 (HER2). "Together, these findings show that an elevated GPR55 expression is associated with the highly aggressive basal/triple-negative breast cancer subtype, higher probability to develop metastases, and therefore poor patient prognosis." (PMID 27340777, 2016). "Here, we show that elevated GPR55 expression in human tumors is associated with the aggressive basal/triple-negative breast cancer population, higher probability to develop metastases, and therefore poor patient prognosis." (PMID 27340777, 2016). "Thus, an elevated GPR55 expression is associated with the basal/triple-negative breast cancer subtype, higher probability to develop metastases, and therefore poor patient prognosis." (PMID 27340777, 2016). "The work presented here cogently shows that activation of GPR55 promotes metastatic responses in vitro and in vivo in triple-negative breast cancer." (PMID 27340777, 2016). "As high tumor aggressiveness is intimately related to the capability of cancer cell dissemination and the establishment of metastatic lesions, we next analyzed whether GPR55 bestows pro-metastatic properties to triple-negative breast cancer cells." (PMID 27340777, 2016).
acute coronary syndrome (1 paper, 2019). Signs and symptoms related to acute ischemia of the myocardium secondary to coronary artery disease. "The phospholipid l‐α‐lysophosphatidylinositol (LPI), an endogenous ligand for GPR55, is elevated in patients with acute coronary syndrome, and a GPR55 antagonist cannabidiol (CBD) reduces experimental ischemia/reperfusion (I/R) injury." (PMID 31149342, 2019).
amyloid (1 paper, 2020). "In any case, the contribution of GPR55 to the neuropathology of AD is supported by additional reports suggesting that LPI deposits are enriched in the outer layer of the amyloid plaque, facilitating the interaction with microglia/macrophages and probably modulating neuroinflammation." (PMID 33167441, 2020).
Ataxia (1 paper, 2013). Ataxia refers to impaired coordination of voluntary muscle movement. "Taken together, these results show that GPR55 KO mice exhibit an ataxia-like phenotype due to motor coordination deficits." (PMID 23565223, 2013).
autoimmune disease (1 paper, 2025). A disorder resulting from loss of function or tissue destruction of an organ or multiple organs, arising from humoral or cellular immune responses of the individual to their own tissue constituents. "We anticipate that the utilization of GPR55-gene-deficient mice may provide insights into its functions in autoimmune diseases and its therapeutic potential." (PMID 40429822, 2025).
Autoimmunity (1 paper, 2013). The occurrence of an immune reaction against the organism's own cells or tissues. "Deletion of cannabinoid receptor genes have not been associated with a sexually dimorphic effects in EAE, yet it was apparent that GPR55 deficient female mice may develop less autoimmunity compared to males and was seen in both C57BL/6.Gpr55-/- and ABH.Gpr55-/- mice." (PMID 24130809, 2013).
brain infarction (1 paper, 2024). Tissue necrosis in any area of the brain, including the cerebral hemispheres, the cerebellum, and the brain stem. "We also found that GPR55 inactivation diminished CD4+T-cell infiltration in the brain, which was accompanied by diminished brain infarction and neurological outcome improvements." (PMID 38334672, 2024).